ESF1 (ESF1 nucleolar pre-rRNA processing protein)
Description:
May constitute a novel regulatory system for basal transcription. Negatively regulates ABT1 (By similarity).
Synonyms: ABTAP; C20orf6; HDCMC28P; bA526K24.1
Tractability: PROTAC: ubiquitination databases record sites on it; its protein half-life has been measured.
Gene: Protein-coding gene on chromosome 20 (13,714,322 to 13,785,409, reverse strand). Ensembl gene ENSG00000089048.
Subcellular location: Nucleus, nucleolus; Nucleus, nucleoplasm
Subcellular location (Human Protein Atlas): Nucleoli; Nucleoplasm
Gene Ontology:
Molecular function: RNA binding
Biological process: rRNA processing
Cellular component: extracellular region; nucleolus; nucleoplasm; nucleus
Genetic constraint (gnomAD): Loss-of-function variants: 46 observed, 68.87 expected, observed/expected ratio (o/e) 0.67, 90% interval 0.53 to 0.85. The upper end of that interval is the gene's LOEUF score, 0.85, which puts it in group 3 of 6, group 1 being the genes least tolerant of losing a copy. Missense variants: 794 observed, 862.12 expected, observed/expected ratio (o/e) 0.92, 90% interval 0.87 to 0.98. Synonymous variants: 278 observed, 279.35 expected, observed/expected ratio (o/e) 1, 90% interval 0.9 to 1.1.
Homologues: Orthologues: chimpanzee ESF1 (98% identical), macaque ESF1 (95% identical), pig ESF1 (87% identical), dog ESF1 (85% identical), guinea pig Esf1 (82% identical), rabbit ESF1 (81% identical), mouse Esf1 (81% identical), rat Esf1 (80% identical), tropical clawed frog esf1 (56% identical), zebrafish esf1 (49% identical), Drosophila melanogaster CG11417 (35% identical), Caenorhabditis elegans F58B3.4 (22% identical).
Diseases named in the same sentence as ESF1 in open-access papers:
ESF1 is named in the same sentence as 9 diseases in open-access papers, as found by Europe PMC text mining. Sharing a sentence is not in itself a finding about the gene and the disease. The quoted sentences say what the papers report.
gastric cancer (2 papers, 2024 to 2025). A primary or metastatic malignant neoplasm involving the stomach. "ESF1 protein plays a prominent role in predicting the recurrence of hepatitis B virus-related hepatocellular carcinoma and the response to gastric cancer chemotherapy." (PMID 39004717, 2024).
Obesity (2 papers, 2022 to 2024). Accumulation of substantial excess body fat. "ESF1 was identified as one of five hub genes that modulate angiogenesis, leading to obesity-induced cardiac injury." (PMID 38674024, 2024). "S1-repressed ESF1 was identified as one of five hub genes responsible for obesity-induced cardiac injury by affecting angiogenesis in the heart." (PMID 38674024, 2024). "ESF1 was also identified as one of five hub genes responsible for obesity-induced cardiac injury by affecting angiogenesis in the heart." (PMID 38674024, 2024). "UTP14A, DKC1, DDX10, PinX1, and ESF1 have been identified as hub genes in obesity-induced pathological changes in the heart and may be involved in obesity-induced cardiac injury by affecting cardiac microcirculatory function." (PMID 35734237, 2022). "UTP14A, DKC1, DDX10, PinX1, and ESF1 may be involved in obesity-induced cardiac injury by affecting angiogenesis in the heart." (PMID 35734237, 2022).
breast carcinoma (1 paper, 2024). "ESF1 promoted the colony formation, accelerated the cell cycle, and enhanced the migration ability of breast cancer cells." (PMID 39004717, 2024). "As the novel proteins discovered in ER + breast cancer, the functions of ESF1 and MIPEP were further discussed and verified in this study." (PMID 39004717, 2024). "In this study, an upregulated expression of ESF1 was observed for the first time in both breast cancer tissue and the MCF-7 breast cancer cell line." (PMID 39004717, 2024). "Subsequent immunohistochemical staining validated the significant upregulation of ESF1 and MIPEP in the ER + breast cancer tissue sections." (PMID 39004717, 2024). "During STRING analysis, we found ESF1, MIPEP, TMEM24, and SART1 were the hub genes in ER + breast cancer’s pathogenesis." (PMID 39004717, 2024). "STRING analysis found ESF1 and MIPEP were the hub genes in breast cancer, whose increased expressions were verified by the IHC staining and western blot." (PMID 39004717, 2024). "The upregulation of ESF1 and MIPEP promoted ER + breast cancer proliferation, which might provide novel targets for the development of new therapies." (PMID 39004717, 2024). "Furthermore, a series of experiments conducted on the MCF-7 cell line revealed that both ESF1 and MIPEP could promote the proliferation of breast cancer cells." (PMID 39004717, 2024). "Therefore, ESF1 and MIPEP proteins played a considerable role in ER + breast cancer development, which might serve as potential therapeutic targets." (PMID 39004717, 2024).
COVID-19 (1 paper, 2024). A disease caused by infection with severe acute respiratory syndrome coronavirus 2. "DAW1, ESF1, KCTD2, USP45, PNMA8A, SYNDIG1L, and CC2D2B are novel genes/proteins that may be linked to COVID-19." (PMID 38674024, 2024).
tumor (2 papers, 2022 to 2024). "Then, as a crucial tumor suppression factor of PCa epithelium, protein SMAD2 is inhibited, resulting in TF ESF1 upregulation and oxidatively induced DNA damage." (PMID 35164166, 2022).
ESF1 also shares sentences with these, for which no sentence is quoted: glioma (1 paper); hepatocellular carcinoma (1); injury (1); osteosarcoma (1).